TNF (tumor necrosis factor)
Diseases named in the same sentence as TNF in open-access papers (continued):
Sharing a sentence is not in itself a finding about the gene and the disease.
rheumatic diseases (continued). "In this study, we investigated two different IGRAs as potentially superior ways of diagnosing LTBI in patients with rheumatic diseases before and during TNF-α antagonist therapy." (PMID 26474294, 2015). "There have been extensive efforts to develop better tools for detection of LTBI in patients with rheumatic diseases who require immunosuppressive agents such as TNF-α antagonist." (PMID 26474294, 2015). "In order to confirm the potential impact of circulating IL-6 for plasma-NGAL levels found in septic patients and patients with rheumatic disease after treatment with an anti-TNF agent, whole blood samples were stimulated with IL-6." (PMID 25893429, 2015). "Based on the results of our study, we suggest that T-SPOT.TB test should be included in the initial evaluation as well as in follow-up protocols for patients with rheumatic diseases receiving TNF-α antagonist therapy." (PMID 26474294, 2015). "GKS are usually served with disease-modifying drugs (DMARDs) or TNF-α inhibitors in the treatment of rheumatic diseases, so that data on monotherapy are limited." (PMID 25549599, 2015). "Results of QuantiFERON-TB Gold In-Tube and T-SPOT.TB tests in initial evaluation of LTBI in patients with rheumatic diseases scheduled for TNF-α antagonist therapy." (PMID 26474294, 2015). "We investigated the characteristics and frequency of neurological adverse events in patients with rheumatic diseases treated with TNFα antagonists in a prospective study using MRI and neurophysiological tests before the initiation of anti-TNFα therapy." (PMID 24938855, 2014). "In the last decade, the introduction of biologic drugs, in particular tumor necrosis factors (TNF)-α blockers, has opened new horizons for patients and rheumatologists in the treatment of PsA and other rheumatic diseases." (PMID 24554385, 2014). "We observed that baseline synovial myeloid, but not lymphoid, gene signature expression was higher in patients with good compared with poor European league against rheumatism (EULAR) clinical response to anti-TNFα therapy at week 16 (P =0.011)." (PMID 25167216, 2014). "In summary, the estimated rate of neurological adverse events in patients with rheumatic diseases treated with TNFα antagonists is 4%." (PMID 24938855, 2014). "Based on these extensive animal data indicating a causal link between TNF-α and cardiac dysfunction in both the acute and chronic setting, clinical trials were launched which tested compounds initially developed for binding of TNF-α in rheumatic diseases." (PMID 23740214, 2013). "The last decade has seen the introduction of biological drugs, e.g. anti-tumor necrosis factor alpha (anti-TNFα) also for paediatric rheumatic disorders." (PMID 23432796, 2013). "The use of biologic treatments, and in particular of TNFα blockers, in rheumatic disorders will probably increase this downward trend." (PMID 20637100, 2010). "The requirement for total joint arthroplasty (TJA) tended to decrease in rheumatic patients before the use of TNFα blockers in rheumatology, thanks to strategies of earlier and more intensive management of recent rheumatic disorders." (PMID 20637100, 2010). "Tumor necrosis factor alpha (TNFα) is among the cytokines that play a major role in the inflammatory process of rheumatic diseases." (PMID 20064207, 2010). "Adalimumab has been recently used for the treatment of several rheumatic diseases and represent the newest biologic agent targeting TNF-α." (PMID 21180427, 2010). "In the present study, we analyze the drug survival rates of TNF antagonists, as a surrogate for their effectiveness, in 488 patients with rheumatic diseases who had switched from one TNF antagonist to another." (PMID 16507128, 2006). "The introduction of biological agents such as TNF-α-blocking agents has dramatically changed the therapeutic approach to rheumatic diseases in recent years." (PMID 15899052, 2005).
rheumatic diseases (continued). "Interestingly, in two retrospective studies, it has been demonstrated that TCZ was more clinically beneficial (according to the DAS28 score) than anti-TNF therapy in patients with AA amyloidosis complicating rheumatic diseases." (PMID 40066438, 2025). "Similarly, in a large cohort of 5224 patients with rheumatic diseases evaluated before TNF inhibitor therapy, positive rates for TST, QuantiFERON-TB Gold In-Tube, and T-SPOT.TB were 29, 17, and 18%, respectively, with concordance levels between 73 and 75%." (PMID 41574365, 2025). "TNF-α inhibitors have been suggested by several studies as responsible for the potential development of neurodegenerative co-morbidities when used as therapeutic agents in rheumatic diseases." (PMID 39459490, 2024). "Consequently, treatment guidelines for IBD and rheumatic diseases have been adapted accordingly and include TNF-α inhibitors in their recommendations, making TNF-α inhibitors an important option in the therapeutic landscape." (PMID 37568441, 2023). "The most notable difference appears when observing the incidence in patients with IBD, with 126.53 cases/100,000 patients treated with a TNF-α inhibitor, 6 times higher than that found in patients with rheumatic disease and almost 4 times higher than the overall incidence found in the meta-analysis." (PMID 38065857, 2023). "However, in patients with rheumatic disease, treatment with TNFα inhibitors shows a protective effect against cardiovascular diseases in comparison with other standard treatments." (PMID 36902036, 2023). "For rheumatic disease, 11 (78.6%) of the patients were using steroids, 8 (57.1%) hydroxychloroquine, 4 (28.6%) methotrexate and sulfasalazine, 2 (14.3%) leflunomide, 1 (7.1%) anti-TNF (etanercept), and 1 allopurinol and colchicine." (PMID 36422487, 2022). "Retrospective series of eight patients showed that treatment with anti-TNF-a is a viable alternative in HIV patients without advanced disease with associated rheumatic diseases refractory to standard therapy." (PMID 35990692, 2022). "We estimated the prevalence of ATB in patients with rheumatic diseases and identified risk factors among those who were not taking anti-TNF biologic." (PMID 34753408, 2021). "Golimumab, a tumor necrosis factor-alpha (TNFa) inhibitor, is used to treat rheumatic diseases." (PMID 32872668, 2020). "Different DNA and RNA aptamers and their modified analogs have been generated against protein biomarkers related to rheumatic diseases, from general markers such as C-reactive protein, TNFα, interleukins, and their receptors, to more specific proteins such as members of the WNT signaling pathway." (PMID 33266394, 2020). "In patients with axial rheumatic diseases, anti-TNFα agents should be preferred." (PMID 32231384, 2020). "Pathogenic cytokines such as TNF-α, interferon-α (IFN-α), and interleukin-6 (IL-6) are critical mediators of autoimmune damages to host cells and tissues and have long been regarded as therapeutic targets for rheumatic diseases." (PMID 32258176, 2020). "Some recent studies have suggested a cardiovascular protective role of anti-TNF-α agents in patients with rheumatic diseases, which may be at least partially explained by the platelet-suppressing role of anti-TNF-α agents." (PMID 33343345, 2020). "Therefore, this study aimed to identify factors favoring starting biosimilars of TNF inhibitors (TNFIs) in patients with rheumatic diseases in the real world when both kinds of drug are available." (PMID 31978121, 2020). "Studies showing that injection of some of the key cytokines produced in rheumatic diseases into HC, such as IL-1β or IL-6, produces fatigue and that biologics targeting IL-6 or TNF-α ameliorate fatigue suggest a role for these molecules in the development of fatigue." (PMID 31685018, 2019).
rheumatic diseases (continued). "Our results, together with others, suggest PLA may be more effective than TNF-α to predict MACCE in patients with rheumatic valve disease, which may be due to the role of PLA in cardiovascular lesions." (PMID 31506454, 2019). "This anti-TNF utilization profile is consistent with the literature, where adalimumab has been the medication most commonly utilized in the treatment of PsA and other rheumatic diseases in Brazil." (PMID 30820348, 2019). "TNF-alpha inhibitors treat several rheumatic diseases effectively, even those in children." (PMID 31296171, 2019). "As the incidence of neoplasms in rheumatic disease patients exposed to anti-TNFs is limited, characterization of neoplasms in this subset of patients is important to guide malignancy screening recommendations in anti-TNF treatment follow up care." (PMID 29540190, 2018). "Moreover, targeting TNF-α, IL-1β, or IL-33 in rheumatic diseases reduce neutrophil recruitment and pain." (PMID 30333752, 2018). "Nineteen patients with rheumatic disease newly scheduled for anti-TNFα therapy were included." (PMID 30043213, 2018). "However, significant improvement in outcome was first accomplished with the introduction of tumor necrosis factor-α inhibitors that were already approved for other inflammatory disorders, including rheumatic diseases." (PMID 29104241, 2017). "As previously reported, increased serum concentrations of the soluble forms of membrane receptor for TNF-α, sTNF-R1, and sTNF-R2, have been found in active BD and demonstrated in several rheumatic diseases, however, controversial are data regarding their putative role as markers of disease activity." (PMID 28289419, 2017). "An analogy for adverse effects that may accompany biological therapy to inhibit HIF-1α may be tumor necrosis factor-α (TNF-α) inhibitors in rheumatic diseases." (PMID 28611671, 2017). "Based on the review of the published cases of patients with rheumatic diseases treated with anti-TNF-α (n = 255), made by Ramos-Casals in 2010, it can be concluded that the risk of HBV reactivation is approximately 38 % (n = 87) in patients HBsAg (+), without preventive antiviral treatment." (PMID 25549599, 2015). "TNF-induced angiogenesis is an important factor in cancer and rheumatic disease." (PMID 23281897, 2012). "This TNF-induced angiogenesis plays a key role in cancer and rheumatic disease." (PMID 23281897, 2012). "Computational gene network analysis revealed a novel molecular system that may play an important role in the TNF-induced angiogenesis seen in cancer and rheumatic disease." (PMID 23281897, 2012). "TNFα blockers were not reintroduced in 14 cases, because the risk of infection was considered too high (n = 12), rheumatic disease remission (n = 1) or patient's refusal (n = 1)." (PMID 20637100, 2010). "However, analyses of switching to another TNF antagonist for patients with spondyloarthritides, such as AS or PsA, are quite limited and often represent a minor subgroup of patients with various rheumatic diseases evaluated in national registries." (PMID 20553600, 2010). "However, serious infections are a major concern in patients with rheumatic diseases treated with anti-TNF-α." (PMID 20633267, 2010). "Moreover, in RA patients, receiving treatment with anti‐TNF therapy for the underlying rheumatic disease was significantly associated with lower odds of COVID‐19‐related hospitalization, in contrast to not receiving any anti‐TNF inhibitor therapy." (PMID 37382255, 2023). "Also, in inflammatory diseases such as rheumatic disorders some lesions could respond to anti-tumor necrosis factor (TNF) and others to anti-CD20 because the different lesions are asynchronous and with different histology even in the same patient." (PMID 31091813, 2019). "In a study of 5224 patients with rheumatic diseases, both TST and IGRA were performed prior to TNF inhibitor therapy." (PMID 41574365, 2025).
rheumatic diseases (continued). "Malic acid dependently decreases the content of tumor necrosis factor alpha (TNF-α), interferon γ (IFN-γ), and interleukins 6 (IL6) and IL10; besides, it reduces symptoms in rheumatic diseases." (PMID 40006847, 2025). "Additionally, these results may support the further treatment selection strategy targeting IL-17A, TNFα, or other Th17-related cytokines, ultimately improving the management of rheumatic diseases by identifying the biologically rational treatment or combination for the patients." (PMID 38292069, 2024). "The tumor necrosis factor (TNF) superfamily contains proteins with proinflammatory and anti-inflammatory activity and has been studied in many diseases, especially in some rheumatic diseases, such as SLE." (PMID 35966818, 2022). "Marked increase of proinflammatory cytokines including IL-1, IL-6, IL-18, TNFα, IFNγ, ferritin and ST2 during MAS attacks portrayed a significant systemic inflammation in patients with various rheumatic diseases, particularly sJIA28,44–47." (PMID 34099791, 2021). "The difference in RHI change from baseline to 6 months between the MTX group and the anti-TNF ± MTX group remained statistically significant after adjustments for age, female gender, rheumatic disease duration, and IA diagnosis." (PMID 29041979, 2017). "The anti-TNF ± MTX and MTX groups had similar characteristics except for a significantly shorter rheumatic disease duration and higher Physicians' Global Assessment (PGA) score in the MTX group (p = 0.043 and p = 0.002, respectively)." (PMID 29041979, 2017). "Based on the crucial role of TNF in inflammation, it was assumed that anti-TNF therapy would be potentially beneficial in chronic inflammatory conditions such as IBD or rheumatic diseases." (PMID 22937039, 2012). "A new era in the treatment of rheumatic diseases began with the development of TNF-α-inhibitors, where TNF-α is a cytokine that performs an important role in inflammatory diseases, which have shown satisfactory results for both joint and skin diseases." (PMID 21804855, 2011). "For example, in rheumatic diseases and MAS, TNF blocking is effective." (PMID 40234407, 2025). "Children with rheumatic diseases have a higher likelihood of developing malignancy than the general population, but the use of TNF inhibitors does not appear to significantly increase this risk." (PMID 40018478, 2025). "Current data demonstrates that individuals with rheumatic diseases on TNF-alpha inhibitors in contrast with those not on DMARD have four times and ten times higher risk for LTBI reactivation in non-endemic and endemic settings, respectively." (PMID 38959249, 2024). "Anti-TNFα therapy is a very effective therapy for rheumatic diseases, but does not modulate all inflammatory pathways." (PMID 37646896, 2023). "We chose to review and discuss the role of anti TNF-α, and not of all biological disease modyfing anti rheumatic diseases (b-DMARDS)." (PMID 35330329, 2022). "For example, IL-37, a member of the IL-1 family which is stimulated by SARS-CoV-2, has been shown to suppress IL-1β, IL-6, TNFα and CCL2 in rheumatic diseases by acting on mTOR and enhancing the AMPK activity, to maintain mitochondrial membrane potential and limit the toxic effects of ROS." (PMID 36389723, 2022). "The use of drugs such as steroids, methotrexate, or anti-TNF in sickle cell patients with rheumatic disease is the same as in patients without sickle cell disease." (PMID 36422487, 2022). "Despite the fact that anti-TNF treatment constitutes a breakthrough in management of RA and other rheumatic diseases, approximately 30% of patients do not achieve any improvement." (PMID 34691284, 2021). "Anti-TNF treatment constitutes a breakthrough in management of rheumatic diseases, although many patients do not achieve significant or any improvement." (PMID 34691284, 2021).
rheumatic diseases (continued). "A clinical trial using the anti-TNF-α antibody infliximab also showed that the use of TNF blocker resulted in lower events of cardiovascular disease in patients with rheumatic diseases compared with no treatment." (PMID 34071276, 2021). "The preferential utilization of interleukin-1R antagonists rather than TNF-a antagonists usually used in articular rheumatism is justified by the dominance of the systemic character of the disease with frequent spikes in fever and seemed efficient." (PMID 34884286, 2021). "Among these proteins, U1–70K (Snrnp70) is the target of self-reactive B cells and T cells in several rheumatic diseases, Ptbp1 is essential for B cell ontogeny and B cell receptor (BCR)-mediated antibody production, HnrnpL involved in the regulation of TNF α gene transcription." (PMID 35006449, 2021). "Moreover, critical proinflammatory cytokines such as IL-6, C-reactive protein (CRP), and tumor necrosis factor (TNF-α) not only play a pivotal role in the inflammatory cascade and evolution of rheumatic diseases but also are independent predictors of CVD." (PMID 34504395, 2021). "Such nonspecific markers as CRP or TNFα serve as precursors of complications and are decreased during remission or low activity of any rheumatic disease." (PMID 33266394, 2020). "The last relapsing patient was a VL treated with L-AmB and TNF-α blockers were not stopped as her rheumatic disease was active presenting a MCL form 20 months after." (PMID 31469834, 2019). "In conclusion, salivary concentrations of CRP, but not of IL-6, in patients with rheumatic disease significantly decrease over the course of successful anti-TNFα therapy and parallel changes in the disease activity." (PMID 30043213, 2018). "The use of anti-TNFα drugs has been one of the best alternatives for the treatment of rheumatic diseases which resist treatment with nonsteroidal anti-inflammatories." (PMID 25276463, 2014). "Microbial agents identified in the present study were similar to those usually observed in TJA infections in patients having or not a rheumatic disorder and in RA patients not exposed to TNFα blockers." (PMID 20637100, 2010). "This was more often involved than in previous studies concerning TJA infections in patients having or not a rheumatic disorder (22 to 45%), and in RA patients not exposed to TNFα blockers (37%)." (PMID 20637100, 2010). "In our previous study, decreased S-specific Ab levels were observed only in patients with IBD treated with anti-TNF, whereas S-specific Ab responses of patients with rheumatic disease were not affected, potentially due to the lower doses of anti-TNF agents used." (PMID 40728886, 2025). "Tumor necrosis factor inhibitors (TNF inhibitors), such as infliximab, adalimumab, and etanercept, are biologic DMARDs that reduce inflammation and bone damage by inhibiting TNF, making them the preferred treatment for many rheumatic diseases, including SAPHO syndrome." (PMID 41451090, 2025). "Two studies from Greece, a non-TB endemic country per the WHO classification, demonstrated that about a third of patients with rheumatic diseases treated with TNF-alpha inhibitors or other biologics had initial negative LTBI screening tests that later converted to a positive screen." (PMID 38959249, 2024). "Furthermore, central and peripheral demyelination can be observed with anti-TNF-α therapy, even in rheumatological disorders, which are not primarily categorized as neurological diseases." (PMID 37483590, 2023). "Under this circumstance, a multi-center, cross-sectional study (ETHERTB) based on tertiary general hospitals was conducted to investigate the prevalence of ATB among patients with rheumatic diseases and to determine risk factors associated with ATB in patients not taking anti-TNF medications." (PMID 34753408, 2021).